TNF (tumor necrosis factor)
Diseases named in the same sentence as TNF in open-access papers (continued):
Sharing a sentence is not in itself a finding about the gene and the disease.
rheumatoid arthritis (continued). "More PVT1 and less miR-145-5p were found in fibroblast-like synoviocytes from people with rheumatoid arthritis (RA-FLSs) when TNF-α was present." (PMID 39530095, 2024). "The enriched KEGG pathways were mainly involved in rheumatoid arthritis, cytokine-cytokine receptor interaction, TNF signaling pathway, osteoclast differentiation, and NF-κB signaling pathway." (PMID 39705460, 2024). "Etanercept is an anti-tumor necrosis factor (anti-TNF) agent that was among the first of its kind in the treatment of rheumatoid arthritis (RA)." (PMID 39246920, 2024). "The top 20 pathways in KEGG involved immune-related pathways such as COVID-19, influenza, hepatitis, rheumatoid arthritis, and inflammatory bowel disease, and involved in immune pathways such as Th17 cell differentiation, IL-17, TNF, and Toll-like receptors." (PMID 38455049, 2024). "For example, the increased production of the cytokine TNF plays a fundamental role in numerous chronic inflammatory disorders such as psoriasis and rheumatoid arthritis." (PMID 39253090, 2024). "Se supplementation can decrease the expression levels of main inflammatory cytokines TNF-α, IL-1β, and IL-6 in inflammatory diseases, such as rheumatoid arthritis, atherosclerosis, and colitis." (PMID 38321393, 2024). "As our knowledge, TNF-α is considered a good mediator of correlating with pathogenesis in rheumatoid arthritis, in carrageenan-induced acute inflammation, and in the chronic arthritic condition in the early phase of inflammation." (PMID 39598225, 2024). "For example, TNF signaling pathway blockers are used to treat rheumatoid arthritis, ankylosing spondylitis, psoriasis, Crohn’s disease, etc.." (PMID 39108259, 2024). "Specifically, treatment of patients with rheumatoid arthritis and periodontitis with TNF blockers such as adalimumab or infliximab has been shown to improve periodontal indices and reduce TNF levels in gingival crevicular fluids." (PMID 39253090, 2024). "Both scutellarin and apigenin exhibit anti-inflammatory effects by modulating TNF signaling and macrophage polarization, suggesting potential therapeutic roles in rheumatoid arthritis, which will be further explored through isolated compound testing." (PMID 39770932, 2024). "In general, in patients with rheumatoid arthritis who have experienced primary failure to an anti-TNF-alpha drug, switching to a different therapeutic target (IL-6, CTLA-4, JAK) is postulated to be more effective than cycling to another anti-TNF-alfa." (PMID 39685848, 2024). "In a collagen-induced arthritis (CIA) murine model of rheumatoid arthritis (RA), this medicine also exhibited a reduction in arthritis clinical signs and decreased systemic TNF-α levels." (PMID 38792574, 2024). "ω-3 poly-unsaturated fatty acids exhibit promise by downregulating TNF-α and IL-6 production, showing efficacy in inflammation-associated anemia in HIV and other inflammatory diseases like rheumatoid arthritis and diabetes mellitus." (PMID 38675885, 2024). "Although TNF-α-blockers are recommended to be used first in the treatment of rheumatoid arthritis in the general population, the value of this recommendation in people with DS remains to be defined." (PMID 39737640, 2024). "Quercetin reduces TNF-α production in several inflammatory models, including colitis, cardiovascular disease, and rheumatoid arthritis." (PMID 39597805, 2024). "TNF α plays a crucial role in controlling inflammatory illnesses like atherosclerosis, psoriasis, asthma, rheumatoid arthritis, and Crohn's disease." (PMID 38629020, 2024). "[Araliaceae] inhibits the inflammatory cytokine production by improving the phosphorylation of IKKα/β and P65, as well as the nuclear translocation of P65, thus exerting anti-rheumatoid arthritis effect in TNF-Tg mice." (PMID 39877388, 2024).
rheumatoid arthritis (continued). "KEGG pathway analysis showed that these genes were involved in PI3K-Akt signaling pathway, MAPK signaling pathway, Rheumatoid arthritis, IL-17 signaling pathway and TNF signaling pathway." (PMID 38336764, 2024). "In an experimental model, auranofin was shown to inhibit NF-κB activation in synoviocytes derived from rheumatoid arthritis patients, resulting in decreased production of pro-inflammatory cytokines such as TNF-α." (PMID 38344607, 2024). "It has been proven from clinical studies that treatment with TNF inhibitors improves the implications of rheumatoid arthritis and has been demonstrated better effectiveness when coupled with methotrexate than when each is given alone." (PMID 39390211, 2024). "Mouse models of rheumatoid arthritis share with human disease bone resorbing cells and strong relation to TNFα expression." (PMID 39082340, 2024). "Among them, five pathways exhibited significant differences, namely Amino sugar and nucleotide sugar metabolism, Viral protein interaction with cytokine and cytokine receptor, IL-17 signaling pathway, Rheumatoid arthritis, and TNF signaling pathway." (PMID 39975580, 2024). "Gene ontology and Kyoto Encyclopedia of Genes and Genomes pathway enrichment results showed that these targets were involved mainly in inflammatory responses and inflammation-related pathways, such as rheumatoid arthritis pathway and TNF signaling pathway." (PMID 39705460, 2024). "Examples such as Etanercept (Enbrel) for rheumatoid arthritis and Abatacept (Orencia), a tumor necrosis factor inhibitor, have achieved clinical success." (PMID 38500602, 2024). "TNF inhibitors are by now considered a first-line therapy for rheumatoid arthritis and a mainstay in the treatment of inflammatory bowel disorders." (PMID 39712842, 2024). "Etanercept (ETN) is a disease-modifying anti-rheumatic drug (DMARD) used in the treatment of rheumatoid arthritis (RA) that works as a tumor necrosis factor inhibitor (TNF inhibitor) by blocking the effects of naturally occurring TNF." (PMID 38738082, 2024). "In progressive rheumatoid arthritis, there is an increase in pro-inflammatory cytokines such as IL- 1β, IL-6, tumor necrosis factor (TNF)-α, and interferon (IFN)-γ, which are most likely derived from the synovial membrane." (PMID 39408157, 2024). "As a common treatment for rheumatoid arthritis (RA), the adverse reactions of TNF-α inhibitors (TNFis) in practical application have garnered attention." (PMID 39029031, 2024). "The pathophysiology of rheumatoid arthritis (RA) involves the contribution of cytokines, specifically TNF-α, IL1-β, IL-6, and IL-8, which play significant roles in the process of synovial inflammation and joint destruction by inducing MMP expression." (PMID 38254696, 2024). "In 2022, the Oral Rheumatoid Arthritis Trial (ORAL surveillance study) found a higher risk of major adverse cardiovascular events and venous thromboembolic events in patients with RA and cardiovascular risk factors treated with Tofacitinib than with TNF inhibitors." (PMID 38256535, 2024). "In clinical trials in patients with rheumatoid arthritis, baricitinib reduced inflammation as much as or more than neutralizing TNF." (PMID 39596013, 2024). "For instance, the overexpression of tumor necrosis factor (TNF)-like cytokine 1A in the synovium of rheumatoid arthritis patients correlates with both disease activity and atheromatous plaque height and the formation of new plaques." (PMID 39062180, 2024). "GRN competitively binds with TNFR1/2 to disrupt TNF-α function, which in turn leads to increased IL-10 production in T regulatory cells in conditions such as rheumatoid arthritis and inflammatory bowel disease." (PMID 39143467, 2024). "In patients with rheumatoid arthritis, the administration of n-3 PUFAs for 6 months significantly reduced levels of TNF-α, IL-1β, and prostaglandin E2 from the baseline and increased levels of the anti-inflammatory cytokine IL-10." (PMID 38892051, 2024).
rheumatoid arthritis (continued). "IL-1β, IL-6, and TNF are three cytokines implicated in PASC and other inflammatory diseases such as rheumatoid arthritis, with IL-1 also contributing to inflammation in MS." (PMID 37112929, 2023). "In patients with rheumatoid arthritis treated with methotrexate and tumor necrosis factor inhibitors, the posttreatment frequencies of autoreactive mature, naive B cells were elevated and similar to pretreatment." (PMID 36281741, 2023). "One physician described a patient with rheumatoid arthritis.“...very complicated rheumatoid arthritis patient that tried all the TNF blockers...she tried Il-6, she failed." (PMID 37454024, 2023). "Anti-TNF drugs are used widely to treat immune-mediated inflammatory diseases, including rheumatoid arthritis, Crohn’s disease, and psoriatic arthritis." (PMID 36851532, 2023). "In the STRASS study (Spacing of TNF-blocker injections in Rheumatoid ArthritiS Study), patients were randomized to either continuing full-dose TNF inhibitor (etanercept or adalimumab) or tapering it by spacing the injection interval." (PMID 37415053, 2023). "Among the biologic drugs, those that act on TNFα were developed first and tested in adults with rheumatoid arthritis, with positive results." (PMID 37436237, 2023). "In confirmation, TNF-α has been shown to play active roles in the development of inflammatory joint disorders such as rheumatoid arthritis (RA), which causes extensive juxta-articular bone degradation, and ankylosing spondylitis (AS), which causes simultaneous bone breakdown and excessive formation." (PMID 37109361, 2023). "In anti-TNF-α therapy in patients with rheumatoid arthritis, functional magnetic resonance imaging shows that anti-TNF-α treatment rapidly alters the brain’s response to pain peripheral stimuli and improves patients’ sense of well-being." (PMID 36838809, 2023). "Trials of tumour necrosis factor α (TNF-α) inhibitors in rheumatoid arthritis had the lowest proportion with ≥2 comorbidities (12%)." (PMID 36649256, 2023). "On average, participants in trials of TNF-α drugs in rheumatoid arthritis had the lowest mean baseline EQ-5D index value at 0.74 (0.08)." (PMID 36649256, 2023). "TNF alpha inhibitors are currently used to treat multiple inflammatory conditions such as rheumatoid arthritis, psoriasis, inflammatory bowel disease, and ankylosing spondylitis." (PMID 37284022, 2023). "A TNF-α siRNA/artemisinin co-delivery nano-microplex (MTAsi@MG) is further prepared by immobilization of TNF-α siRNA/lipoplex on porous microfluidic HA microspheres, which were in situ injected for Rheumatoid Arthritis Therapy." (PMID 38017573, 2023). "In rheumatoid arthritis, TNF-α is known as the main inflammatory cytokine and has been found in high concentrations in patients’ serum." (PMID 37370974, 2023). "In human beings, VNS through cervical stimulation for the treatment of rheumatoid arthritis reduced TNF concentrations for up to 84 days, showing improvement in the severity of the disease." (PMID 37901799, 2023). "The aim of this study is to identify the nailfold videocapillaroscopic abnormalities in rheumatoid arthritis and psoriatic arthritis patients and analyze the correlation between their evolution and 12 months of anti-TNF-α therapy." (PMID 37370974, 2023). "In November 1998, the US the first Food and Drug Administration (FDA) authorized Etanercept, the first anti- tumor necrosis factor inhibitors (TNFi), for the treatment of moderate to severe rheumatoid arthritis (RA)." (PMID 38239345, 2023). "Etanercept is a chimaeric monoclonal TNF‐alpha antibody, used in the therapy of autoimmune diseases such as rheumatoid arthritis or plaque psoriasis." (PMID 36751314, 2023). "For example, our laboratory has reported that miR-17 negatively regulates TNF-α inflammatory signaling but that its expression is unusually low in rheumatoid arthritis synovial fibroblasts (RASFs)." (PMID 38264662, 2023).
rheumatoid arthritis (continued). "The most common ADRs for all five TNFα inhibitors were rash, arthralgia, rheumatoid arthritis, headache, pneumonia, psoriasis, nausea, diarrhea, and pruritus." (PMID 37554981, 2023). "Early research on rheumatoid arthritis (RA) showed that the G/A point mutation at locus TNFα +489 could increase the susceptibility to RA, and it was also related to radiographic damage in RA." (PMID 37654943, 2023). "It is reported that caffeic acid alleviates inflammatory response in rheumatoid arthritis by repressing IL-6 and TNF-α." (PMID 37372012, 2023). "There was also an interaction among the essential oil compositions citral and methyl palmitate, the target TNF, and rheumatoid arthritis." (PMID 35702766, 2023). "These genes were also enriched in “rheumatoid arthritis”, “tumor necrosis factor (TNF) signaling pathway”, “IL-17 signaling pathway,” and “osteoclast differentiation” pathways in KEGG." (PMID 37545537, 2023). "In rheumatoid arthritis patients, tumor necrosis factor-α inhibitors (TNFis) at Term 3, and older age, glucocorticoids, and abatacept at Terms 2 and 3 were risk factors for reduced responses." (PMID 36569794, 2023). "We previously observed protein expression of CCL28 and CCR10 to be upregulated by LPS and pro-inflammatory cytokines such as TNF-α and IL-6 in monocytes and macrophages isolated from patients with rheumatoid arthritis (RA)." (PMID 36713846, 2023). "Excess production of TNF-α has been identified as a key factor in the pathogenesis of autoimmune diseases such as rheumatoid arthritis, inflammatory bowel disease, and psoriasis." (PMID 37664349, 2023). "Many studies and meta-analysis found that platelet count can be reduced by anti-TNF-α therapy in SpA patients and other autoimmune diseases such as rheumatoid arthritis and psoriasis." (PMID 36922788, 2023). "For KEGG analysis, cytokine–cytokine receptor interaction, TNF signaling pathway, IL-17 signaling pathway, and rheumatoid arthritis were significantly enriched." (PMID 37350944, 2023). "On the intercellular level, existing TNF-α inhibitors like the well-studied Infliximab, approved for conditions such as rheumatoid arthritis, offer a promising therapeutic intervention." (PMID 37965310, 2023). "The KEGG analysis results revealed that most of the genes were involved in rheumatoid arthritis and TNF signaling pathways." (PMID 37069673, 2023). "Does tumor necrosis factor alpha inhibition promote or prevent heart failure in patients with rheumatoid arthritis?" (PMID 36877237, 2023). "Rheumatoid arthritis (RA) is an autoimmune disease that primarily affects the synovial membranes and causes excessive production of pro-inflammatory cytokines and chemokines, such as tumor necrosis factor (TNF)-α and interleukin (IL)-6 in synovial membranes." (PMID 37298711, 2023). "The common ADRs of all five TNFα inhibitors were rash, arthralgia, rheumatoid arthritis, headache, pneumonia, psoriasis, nausea, diarrhea, and pruritus." (PMID 37554981, 2023). "In the current study, serum levels of TNF-α were determined to evaluate the severity of rheumatoid arthritis." (PMID 37626711, 2023). "Reduction in tumor necrosis factor (αTNF) and interleukin-6 (IL-6) activities is a widely utilized strategy for the treatment of rheumatoid arthritis (RA) with a high success rate." (PMID 36836953, 2023). "Although the roles of IL-6 and TNF-α in rheumatoid arthritis and in chronic chikungunya arthritis are well established, we saw a reduction during the acute phase." (PMID 38235127, 2023). "Immunobiological drugs such as TNF-α inhibitors are valuable in rescue therapy for autoimmune diseases such as rheumatoid arthritis and inflammatory bowel disease (IBD), but they increase the risk of infectious complications." (PMID 38065857, 2023). "For example, TNFα exists in a membrane-bound form on the EVs released by synovial fibroblasts in rheumatoid arthritis patients, exerting its biologically active function." (PMID 37239071, 2023).
rheumatoid arthritis (continued). "KEGG pathway analysis of 10 key driver genes and 34 selected genes was enriched for genes involved in rheumatoid arthritis, the TNF-α signaling pathway, and the IL-17 pathway." (PMID 38002046, 2023). "As a tumor necrosis factor (TNF) inhibitor, adalimumab is indicated to treat inflammatory disorders, including psoriasis, rheumatoid arthritis, and inflammatory bowel disease." (PMID 37781032, 2023). "Patients with rheumatoid arthritis (RA) are prone to muscle atrophy due to inflammatory cytokines such as tumor necrosis factor α (TNFα) and interleukin 6 (IL-6)." (PMID 37041556, 2023). "TNFα antagonist use has been linked with a reduced risk of MI and development of acute coronary syndrome, highlighting anti-TNFα therapy as a promising anti-atherosclerotic therapy in rheumatoid arthritis patients." (PMID 36902036, 2023). "Because NG-R1 was shown to alleviate rheumatoid arthritis in TNF-Tg mice by promoting lymphatic drainage function via inhibition of the TNF-α signaling pathway, so we validated it in the inflammatory signaling pathway." (PMID 36713827, 2023). "Tumor necrosis factor-alpha (TNF-α) inhibitors have proven to be effective drugs for various rheumatologic diseases, such as rheumatoid arthritis, psoriasis, and inflammatory bowel diseases." (PMID 37664349, 2023). "In adults with rheumatoid arthritis, several studies have shown that anti-TNF treatment increases insulin sensitivity." (PMID 36860845, 2023). "Among these the differentially expressed genes were involved in NF‐ĸB, TNF, rheumatoid arthritis, and chemokine signalling pathways as well as many other biological processes related to angiogenesis." (PMID 36965158, 2023). "TNF-a antagonist-induced granulomatous disease is rare; thus, only four (0.57%) cases were identified among 697 patients with rheumatoid arthritis." (PMID 37250639, 2023). "TNF-α is widely involved in autoimmune/inflammatory diseases, such as rheumatoid arthritis (RA), inflammatory bowel disease (IBD), ankylosing spondylitis (AS) arteriosclerosis, psoriasis (PS), and noninfectious uveitis (NIU)." (PMID 37554306, 2023). "The top 6 KEGG pathways were IL-17 signaling pathway, chemokine signaling pathway, legionellosis, TNF signaling pathway, and rheumatoid arthritis." (PMID 36798787, 2023). "Despite these findings, TNFα antagonism has been clinically therapeutic in inflammatory diseases such as RA (rheumatoid arthritis), ankylosing spondylitis, inflammatory bowel disease, and psoriasis, as well as various off-label indications." (PMID 37849737, 2023). "IL-7 has been found to effectively stimulate the production of IFNγ and TNFα in rheumatoid arthritis and IL-17 in spondyloarthritis." (PMID 37047315, 2023). "In addition, TNF-α may represent a metabolite, providing cross-talk between inflammatory adipose tissue and high cardiometabolic risk, as patients with rheumatoid arthritis responding to anti-TNF-α therapy had a lower frequency of myocardial infarction compared to non-responders." (PMID 36830779, 2023). "Another research study showed that GA significantly decreased TNF-alpha, the erythrocyte sedimentation rate, and the number of swollen and tender joints, as well as the disease severity in rheumatoid arthritis patients." (PMID 36671523, 2023). "The critical role of TNFα in controlling Mtb in infected individuals became obvious when patients with rheumatoid arthritis treated with anti-TNF monoclonal antibodies frequently progressed to active TB." (PMID 38035095, 2023). "Real-world surveys based on the FAERS database found that more than half of anti-TNF therapy was used to treat rheumatoid arthritis." (PMID 37554981, 2023). "The other study compared conventional DMARD, anti-TNF, and abatacept therapies in patients with rheumatoid arthritis." (PMID 37893136, 2023). "Tumor necrosis factor-alpha (TNF-α) inhibitors have been shown to be well tolerated among patients with rheumatoid arthritis, inflammatory bowel disease, and psoriasis." (PMID 37664349, 2023).